TKTL1 (transketolase like 1)
Diseases named in the same sentence as TKTL1 in open-access papers (continued):
Sharing a sentence is not in itself a finding about the gene and the disease.
diabetes (2 papers, 2019 to 2022). "Together these results support our hypothesis that TKTL1 and TKTL2 are functional transketolases and thus opens up the possibility that altered activity/function may be implicated in diseases such as diabetes and cancer." (PMID 30646877, 2019). "Some researchers have suggested TKTL1 and TKTL2 are functional transketolases and represent novel therapeutic targets for diabetes and cancer 20, 45-47." (PMID 35711845, 2022). "Our data support the hypothesis that TKTL1 and TKTL2 are functional transketolases and represent novel therapeutic targets for diabetes and cancer." (PMID 30646877, 2019).
head and neck squamous cell carcinoma (2 papers, 2011 to 2013). A squamous cell carcinoma that arises from any of the following anatomic sites: lip and oral cavity, nasal cavity, paranasal sinuses, pharynx, larynx, and salivary glands. "Specifically in head and neck squamous cell carcinoma TKTL1 is activated by promoter hypomethylation and drives carcinogenesis by increased aerobic glycolysis and hypoxia inducible factor 1 alpha (HIF-1α) stabilization." (PMID 24304513, 2013).
infertile (2 papers, 2015 to 2022). "For a subset of testis-specific candidates, i.e., TKTL1, LDHC, and PGK2, their germ cell expression was validated and it was demonstrated that such markers could be distinguished between semen from fertile and infertile men." (PMID 26097523, 2015).
pancreas carcinomas (2 papers, 2006 to 2022). "It is suggested that S100A11 may regulate PPP in a TKTL1-TKT heterodimer-independent manner, which highlighting clinically a significant association between S100A11 and TKT in pancreatic cancer." (PMID 35752610, 2022).
rectal cancer (2 papers, 2011 to 2015). A primary or metastatic malignant neoplasm that affects the rectum. "Although TKTL1 expression has been analysed in many solid tumours, to date no such analysis has been done for rectal cancer." (PMID 21854597, 2011).
renal cell carcinoma (2 papers, 2009 to 2024). "Langbein demonstrated that Transketolase was more elevated in metastasizing renal cell cancer and TKTL1 protein was significantly overexpressed in progressing renal cell cancer." (PMID 19331662, 2009). "We found a positive correlation between KIRC and KIRP, which is exactly the hypothesis that TKTL1 expression is involved in T cell energy metabolism in renal cell cancer." (PMID 38675412, 2024). "Thirdly, in the two renal cell carcinoma subtypes, KIRC and KIRP, the expression of TKTL1 and PD-L1 showed different correlation patterns." (PMID 38675412, 2024). "Therefore, considering the correlation between TKTL1 and T cell energy metabolism, we took genes that have been identified to be involved, and we looked at the relationship between TKTL1 expression and KIRC and KIRP in renal cell cancer." (PMID 38675412, 2024).
thyroid cancer (2 papers, 2006 to 2016). "Similarly, earlier studies demonstrated that oxythiamine was not effective in most thyroid cancer cells expressing high TKTL1 and in vivo in normal rat tissues that expressed high TKTL1." (PMID 26907172, 2016).
acute myeloid leukemia (1 paper, 2022). Acute myeloid leukemia (AML) is a group of neoplasms arising from precursor cells committed to the myeloid cell-line differentiation. "In addition, increased levels of TKTL1 have been reported in response to decitabine (DAC) treatment in primary acute myeloid leukemia (AML) samples and correlated to the acquisition of tyrosine kinase inhibitor resistance in chronic myeloid leukemia (CML)." (PMID 35408935, 2022).
adenoma (1 paper, 2017). A neoplasm arising from the epithelium. "TKT expression was higher in hyperplastic lesions and in both benign and malignant tumors compared to the normal mammary gland, while TKTL1 levels were remarkably higher in hyperplastic lesions, simple adenomas and simple carcinomas than in the normal mammary glands (P < 0.05)." (PMID 28143530, 2017). "This hypothesis is further supported by the higher TKTL1 expression in simple adenomas than in complex carcinomas (P < 0.001)." (PMID 28143530, 2017). "Significant positive correlations were observed between TKT and TKTL1 expression in normal mammary gland (ρ = 0.59, P < 0.05), while a negative correlation was observed for complex adenomas (ρ = −0.39, P = 0.003)." (PMID 28143530, 2017).
Alzheimer disease (1 paper, 2008). A progressive, neurodegenerative disease characterized by loss of function and death of nerve cells in several areas of the brain leading to loss of cognitive function such as memory and language. "We propose, that the protective capacity of the TKTL1-pathway is not sufficient to compete with a chronic glycaemic overload, a condition which favours the development of several civilization-related diseases like the Alzheimer disease, type 2 diabetes, and the metabolic syndrome." (PMID 19812737, 2008).
astrocytomas (1 paper, 2009). "In accordance with the present results, we have not found a correlation between TKTL-1 expression and prognosis in tumors of lower malignancy like astrocytomas <grade IV or granulosa cell tumors of ovary." (PMID 19545368, 2009).
Azoospermia (1 paper, 2025). Absence of any measurable level of sperm,whereby spermatozoa cannot be observed even after centrifugation of the semen pellet. "What role does TKTL1 gene serve in human spermatogenesis and does its mutation trigger non-obstructive azoospermia (NOA)?" (PMID 40680550, 2025).
bladder carcinomas (1 paper, 2006). "Analysis of bladder carcinomas showed absence of TKTL1 reactivity in superficial, nonmuscle-invading tumours, whereas invasive tumours showed immunoreactivity." (PMID 16465194, 2006).
colon adenocarcinoma (1 paper, 2006). "In order to study the correlation of TKTL1 expression on clinical–pathological parameters, a retrospective survey of surgical samples from 70 patients (55 men and 15 women, median age of 60±15 years) with colon adenocarcinoma was performed." (PMID 16465194, 2006).
Gastric tumors (1 paper, 2008). "Gastric tumors and granulosa cell tumors of the ovary were also found to express high amounts of TKTL1 (36.9%; 81%)." (PMID 18700018, 2008).
kidney cancer (1 paper, 2024). Primary or metastatic malignant neoplasm involving the kidney. "Moreover, higher TKTL1 expression levels were significantly associated with a better prognosis in early-stage kidney cancer (Stage 1 (OS HR = 0.45, p = 0.0072)) patients, whereas this association was not evident in the late stage." (PMID 38675412, 2024). "In this study, we investigated whether the mRNA expression of TKTL1 is associated with the levels of immune infiltration in different forms of kidney cancer using the TIMER database." (PMID 38675412, 2024). "The results strongly indicated that TKTL1 has a distinct function in the infiltration of the immune system in various forms of kidney cancer, resulting in an improved prognosis for KIRC." (PMID 38675412, 2024). "Some studies have shown the influence of TKTL1 in cancers, but it has been rarely reported in kidney cancer." (PMID 38675412, 2024). "In this study, we found that the correlations between PD-L1/PD1 and TKTL1 expression in three types of kidney cancers (KIRC, KIRP, and KICH) are the same." (PMID 38675412, 2024). "We found a significant downregulation of TKTL1 expression in three different kidney cancer types: KICH, KIRC, and KIRP, when compared to normal tissues." (PMID 38675412, 2024). "Using these methods, we determined that TKTL1 significantly affects the prognostic potential in different types of kidney cancer patients." (PMID 38675412, 2024). "Here, we employed independent datasets from TCGA within the TIMER2 platform to ascertain the expression levels of TKTL1 in kidney cancers." (PMID 38675412, 2024). "The mRNA expression levels of TKTL1 in kidney cancer and adjacent normal tissues were examined by analyzing the TKTL1 mRNA expression levels through the prominent online database TIMER2." (PMID 38675412, 2024). "Piperine and glibenclamide may be effective therapeutic TKTL1 agonists, providing a theoretical basis for the clinical treatment of kidney cancer." (PMID 38675412, 2024). "Furthermore, the role of TKTL1 in the prognosis and tumor infiltration of immune cells in various cancers, particularly kidney cancer, remains unknown." (PMID 38675412, 2024). "Our work implies that TKTL1 may be a promising prognostic biomarker for KIRC patients that respond to anti-PD-1 therapy, providing insight into the possible role of TKTL1 in tumor immunology and its application as a prognostic biomarker and novel therapeutic target for kidney cancer." (PMID 38675412, 2024). "Through examining the correlation between the levels of TKTL1 expression and various clinical characteristics, our goal is to uncover the mechanism and significance of TKTL1 expression levels in different types of cancer, particularly in individuals with varying clinical stages of kidney cancer." (PMID 38675412, 2024). "Therefore, glibenclamide and piperine may be effective therapeutic TKTL1 agonists, providing a theoretical basis for the clinical treatment of kidney cancer." (PMID 38675412, 2024). "We further explored the prognostic impact of TKTL1 expression and immune infiltration in KIRC, KIRP, and KICH, and we studied the relationship between different immune cells and kidney cancer OS." (PMID 38675412, 2024). "We also demonstrate that there would be better prospects for kidney cancer when PPARA and TKTL1 are co-treated." (PMID 38675412, 2024). "So, there would be better prospects for kidney cancer when PPARA and TKTL1 are co-treated." (PMID 38675412, 2024).
kidney chromophobe (1 paper, 2024). "The underlying mechanism might be that the TKTL1 expression level was positively associated with devious immunocytes in kidney renal clear cell carcinoma (KIRC) rather than in kidney renal papillary cell carcinoma (KIRP) and kidney chromophobe (KICH)." (PMID 38675412, 2024).
lymph node metastasis (1 paper, 2013). "TKTL1 expression was significantly associated with tumor size (pT3/4, p = 0.0018), advanced tumor stages (UICC III/IV, p < 0.0001), cervical lymph node metastasis (pN1-3, p = 0.0008), and extracapsular spreading of lymph nodes (p = 0.0099)." (PMID 24304513, 2013).
male infertility (1 paper, 2025). The inability of the male to effect fertilization of an ovum after a specified period of unprotected intercourse. "Although at this stage it is difficult to conclude whether TKTL1 is essential for a successful spermatogenesis, this study may provide a further understanding of genomic cases of male infertility contributing to the platform of genes that should be recognized as causative of NOA." (PMID 40680550, 2025).
malignant glioma (1 paper, 2018). A grade III or grade IV glioma arising from the central nervous system. "Our present study therefore expands the scarce data on the role of TKTL1 in malignant glioma." (PMID 30044385, 2018).
metastatic melanoma (1 paper, 2016). A melanoma that has spread from its primary site to another anatomic site. "We examined TKTL1 by immunohistochemistry using a tissue microarray (TMA) comprising 81 tumors from patients with stage III and IV metastatic melanoma." (PMID 26907172, 2016). "Melanocytes were found to be hypermethylated which correlated with the lack of TKTL1 expression in those cells, while metastatic melanoma cell lines tested showed reduced methylation levels when compared to melanocytes." (PMID 26907172, 2016).
metastatic tumours (1 paper, 2021). "Moreover, an enzyme that regulates the non-oxidative phase of the PPP, transketolase-like protein 1 (TKTL1), increases in expression during PCa progression, being highest in metastatic tumours." (PMID 34382934, 2021).
monocytic leukemia (1 paper, 2022). "This study combined targeted metabolomics and transcriptomics profiling for a comparative analysis of a stable, acute, monocytic leukemia cell line with a TKTL1 knockdown and a wild-type counterpart, in order to discern TKTL1’s role in metabolic adaptation under the state of hypoxia." (PMID 35408935, 2022).
neuroblastoma (1 paper, 2022). Neuroblastoma (NB) is the most common solid, extracranial childhood tumor. "In this study, we quantified the TKTL1 and DNaseX/Apo10 mRNA levels of seven neuroblastoma patients using RT-PCR." (PMID 35864157, 2022). "Therefore we analysed seven neuroblastoma samples for TKTL1 and DNaseX/Apo10 mRNA." (PMID 35864157, 2022). "Peripheral blood macrophages of patients with neuroblastoma (n = 38) and healthy individuals (control group, n = 37) were labelled (CD14+/CD16+) and assessed for TKTL1, Apo10 and GD2 using the EDIM technology." (PMID 35864157, 2022).
neuroendocrine tumors (1 paper, 2023). "Furthermore, TKTL1 which was upregulated in the de novo NEPC region in the present case, is an important protein that promotes invasion and metastasis and is highly expressed in neuroendocrine tumors (NETs)." (PMID 37240308, 2023).
type 1 diabetes (1 paper, 2023). "Our previous study on type 1 diabetes demonstrated that SUMOylation positively regulates key metabolic enzymes, including Glyceraldehyde-3-phosphate dehydrogenase (GAPDH), citrate synthase, and transketolase-like protein-1 (TKTL1), within the Krebs cycle." (PMID 37947589, 2023).
Werner syndrome (1 paper, 2024). "Consequently, in Werner's syndrome, a genetic mutation in the Werner protein causes the TKTL1 protein expression to be switched off, resulting in high levels of radicals and DNA damage, leading to a significantly shortened lifespan." (PMID 39444815, 2024).
tumor (61 papers, 2006 to 2026). "It is particularly notable that the majority of marker sets in these immunocytes show significant associations with TKTL1 expression in the tumor tissue of KIRC and KIRP patients." (PMID 38675412, 2024). "The expression of TKTL1, encoding the enzyme involved in the pentose phosphate pathway, was upregulated in tumor-induced memory NK cells." (PMID 38534374, 2024). "TKTL1 over expression has been associated with the malignant cells and is presumably involved in the metabolic switch leading to this glycolytic tumor phenotype." (PMID 31027492, 2019). "While overexpression of mutated TKTL1 has been reported in urothelial and colorectal cancer and correlated with tumor invasiveness as well as predicted poor patient outcome, TKT and TKTL2 expression were not altered in this study." (PMID 28553614, 2017). "The causal role of the activation of the TKTL1 gene in tumor cells—which causes a switch to a fermentative metabolism and goes hand-in-hand with increased glucose intake, increased lactic acid production and invasive growth behavior—was recently proven again." (PMID 28425973, 2017). "By using the biomarkers Apo10 and TKTL1 it is now possible to detect neoplasia associated changes in the two fundamental biophysical processes of endonuclease/apoptosis activation and glucose/energy metabolism." (PMID 24304513, 2013). "No transketolase activity of TKTΔ38 can be detected for conversion of physiological sugar substrates thus arguing against an intrinsically encoded enzymatic function of TKTL1 in tumor cell metabolism." (PMID 23118983, 2012). "TKTL1 is an enzyme-linked to abnormal glucose metabolism and tumor development." (PMID 37980488, 2023). "Furthermore, TKTL1 causes tumor metabolic reprogramming and orchestrates aerobic glycolysis, fatty acid and nucleic acid synthesis, glutamine metabolism, protection against oxidative stress, and cell proliferation." (PMID 36009359, 2022). "Any kind of tumor cell damage causing leakage of Apo10 and TKTL1 could be picked up by myeloid cells." (PMID 32438648, 2020). "The clinical relevance of these two fundamental biophysical processes is underlined by the fact, that Apo10 and TKTL1 presence in tumors represent two independent processes which are associated with advanced tumor stages and reduced tumor-specific survival in OSCC." (PMID 24304513, 2013). "Positive Apo10 and TKTL1 expression were associated with recurrence of the tumor." (PMID 24304513, 2013). "TKTL1 mainly regulates glycolysis, and its high expression in malignant tumor cells is closely related to tumor invasiveness, therapeutic resistance, and prognosis." (PMID 39644404, 2025). "TKTL1 also enables tumor cells to rapidly metabolize glucose through glycolysis, generate energy, and discharge large amounts of lactic acid." (PMID 39644404, 2025). "The remarkable innovation lies in the macrophage-based detection experimental system utilized for Apo10 and TKTL1, where the tumor material within macrophages remains undiluted by blood, achieving a high concentration within the cells." (PMID 39644404, 2025). "DNA hypomethylation also plays a role in the activation of genes involved in tumor metabolism, such as Transketolase-like 1 (TKTL1)." (PMID 40573249, 2025). "Apo10 serves as a predictor of tumor formation, whereas TKTL1 is closely correlated with tumor aggressiveness and prognosis." (PMID 39644404, 2025). "Taken together, these findings indicate that although the Apo10 concentration can usually be detected at the beginning of malignant tumors, the expression of TKTL1 starts to increase only with tumor malignancy and invasiveness." (PMID 39644404, 2025). "We chose the types of cancer in which the levels of TKTL1 expression exhibit a notable inverse relationship with tumor purity in TIMER, as well as a noteworthy direct relationship with prognosis." (PMID 38675412, 2024).